AFP (alpha fetoprotein)
Diseases named in the same sentence as AFP in open-access papers (continued):
Sharing a sentence is not in itself a finding about the gene and the disease.
gastric cancer (continued). "Given the rare and late presentation of the disease, AFP-negative HAS should be included in the differential diagnosis in patients with suspicion for gastric cancer." (PMID 33415058, 2020). "Our study defined “AFPGC” as “serologic AFP positive and histologically without hepatoid differentiated gastric cancer”." (PMID 31915699, 2019). "APFGC has a higher incidence of venous invasion and liver metastasis compared with AFP negative gastric cancer." (PMID 31915699, 2019). "On one hand, gastric cancer without AFP producing cannot exclude the possibility of hepatoid adenocarcinoma." (PMID 30212993, 2018). "SALL4 and GPC3 are also highly expressed in AFP-producing gastric cancers, but there are no reports on their expression in AFP-producing colorectal cancers." (PMID 30191347, 2018). "Notably, as observed in gastric cancers in KC-OSKM mice, SALL4, LIN28A, and LIN28B were frequently co-expressed in human AFP-producing gastric cancers, suggesting that these cancers exhibit activation of the pluripotency-related regulatory network." (PMID 29802314, 2018). "AFP-producing gastric cancers are associated with aggressive clinical behavior and poorer prognosis compared to AFP-negative gastric cancer because of a significantly higher incidence of vascular invasion, lymph node metastasis, and liver metastasis." (PMID 30191347, 2018). "The diagnostic and prognostic significance of carcinoembryonic antigen (CEA), carbohydrate associated antigen 19–9 (CA19–9), alpha-fetoprotein (AFP) and cancer antigen 125 (CA125) in early gastric cancer have not been investigated yet." (PMID 29121872, 2017). "The detection sensitivity of classical biomarkers and epidemiological factors for gastric cancer was 13% (CEA), 6% (AFP), 6% (CA125), 3% (CA15-3), 14% (CA19-9), 29% (CA72-4), 36% (cytokeratin 19), 13% (NSE), 18% (overweight), 25% (smoking), 10% (alcohol) and 7% (previous history of cancer)." (PMID 28925386, 2017). "However, no studies have investigated the prognostic value of normal CEA, CA19-9, AFP, and CA125 levels in gastric cancer patients." (PMID 27533455, 2016). "According to the mechanisms of AFP upregulates the expression of VEGF-C, the inhibitors of VEGFR or VEGF might be potential drugs to cure this special type of gastric cancer patients." (PMID 27631210, 2016). "Compared with AFP-negative gastric cancer, AFP-producing gastric cancer possesses higher proliferative activity, weaker apoptosis and richer neovascularization." (PMID 27995033, 2016). "It was reported that AFP, CEA and CA19-9 are independent prognostic factors for gastric cancer." (PMID 27418046, 2016). "We conclude that the combined assessment of CA19-9, AFP and CA125 levels could have prognostic value in gastric cancer (P<0.001)." (PMID 27533455, 2016). "Thus, CA19-9, AFP, and CA125 were tested in univariate and multivariate analyses as prognostic predictors of gastric cancer." (PMID 27533455, 2016). "Therefore, the purpose of this study was to explore the prognostic values of normal, preoperative CEA, CA19-9, AFP, and CA125 levels in gastric cancer." (PMID 27533455, 2016). "Furthermore, we evaluated the expression of AFP and STAT3 by immunohistochemistry in human gastric cancer samples." (PMID 23382965, 2013). "In the 24 AFP-negative gastric cancer samples, 8 (33%) primary tumors were positive and 16 (67%) were negative for STAT3 expression." (PMID 23382965, 2013). "Serum AFP, CEA, CA125 and CA19-9 levels were measured in 149 patients with gastric cancer, 111 patients with benign gastric diseases and 124 healthy people, who visited the First Affiliated Hospital of Nanchang University from May 2011 to May 2012." (PMID 23672279, 2013). "AFPGC, as represented by the production of AFP, exhibits higher proliferative activity, weaker apoptosis, and richer neovascularization than AFP-negative gastric cancers." (PMID 23382965, 2013).
gastric cancer (continued). "The clinicopathologic entity was broadened to include gastric carcinoma showing hepatic differentiation without production of AFP." (PMID 21592404, 2011). "In 1986, the clinicopathologic entity was broadened to include gastric carcinoma showing hepatic differentiation without the production of AFP." (PMID 19674468, 2009). "It has been reported that AFP-producing gastric cancer has high proliferative activity, weak apoptotic activity, and rich neovascularization compared with AFP-negative gastric cancer." (PMID 17634124, 2007). "Additionally, AFP acts as a co-chaperone of heat shock protein 90 (HSP90), stabilizing oncoproteins c-MYC and c-MET, thereby facilitating tumor progression in liver and gastric cancers." (PMID 40485723, 2025). "Gastric cancer with differentiated liver cells in pathological morphology can be diagnosed as HAS regardless of whether serum AFP or AFP staining is positive." (PMID 40235542, 2025). "Furthermore, we showed that even in the AFP-negative cases, 30% of gastric cancer cases with metachronous liver metastasis had the GAPEP phenotype." (PMID 38355790, 2024). "Although elevated levels of c-Myc and c-Met have been reported in HCC and gastric cancer patients, it is not yet certain whether these proteins are responsible for AFP-promoted progression of liver and gastric cancers." (PMID 39135041, 2024). "Surprisingly, qRT-PCR results in liver and gastric cancer cells transfected with AFP siRNA or plasmids showed no impact on their transcription levels, despite a positive correlation between AFP protein expression and that of c-Myc and c-Met in western blot data." (PMID 39135041, 2024). "Considering the difficulty of biopsy diagnosis for HAS and the serum AFP test was not universal for gastric cancer in most medical center, CA19–9 could function as a valuable prognostic index for HAS patients." (PMID 36647059, 2023). "There are some clinically useful tumor markers for monitoring gastric cancer, including CEA, carbohydrate antigen 19-9 in the sialyl Lewis A group (CA19-9), sialyl Tn antigen (STN), cancer antigen 72-4 (CA72-4), cancer antigen 125 (CA125), and alpha-fetoprotein (AFP)." (PMID 32347434, 2020). "AFP-GC may not be a poor prognostic factor for patients undergoing hepatectomy for liver metastases from gastric cancer or this may be false negative due to insufficient power of this study." (PMID 32093729, 2020). "However, no study on the surgical treatment of liver metastasis from gastric cancer have mentioned of AFP-GC." (PMID 32093729, 2020). "However, some patients present a normal AFP level, and some AFP producing gastric cancer is not hepatoid adenocarcinoma." (PMID 30212993, 2018). "We noted that there were two patients complicated with PVTT, which is a special characteristic of AFP-related gastric cancer; a high rate of PVTT in AFP-producing gastric cancer (14.9% in our study) may indicate high intendancy of vascular invasion and angiogenesis." (PMID 29434637, 2017). "Thus, the combination of CA19-9, AFP and CA125 levels could further increase the predictive value for the prognosis of gastric cancer." (PMID 27533455, 2016). "In addition, it is not well defined that alteration of pre-operative serum AFP level or post-operative serum AFP level can be utilized for predicting and monitoring gastric cancer recurrence." (PMID 27995033, 2016). "However, as a retrospective study, we could only evaluate the prognostic value of AFP, CEA, CA19-9, and CA50 for gastric cancers, which were evaluated in our institute." (PMID 22540862, 2012). "Furthermore, no case of gastric carcinoma with synchronous expression of AFP and neuroendocrine markers was observed." (PMID 22482081, 2012). "Therefore, gastric cancer showing hepatic differentiation without production of AFP was a clinicopathologic entity of HAC." (PMID 21592404, 2011).
gastric cancer (continued). "In a xenograft model of AFP-producing gastric cancer, 5-FU, doxorubicin, and epirubicin did not induce suppression of tumor growth; however, MMC and cisplatin may be active to some extent." (PMID 21592404, 2011). "In addition, clinical parameters contributing significantly to gastric cancer screening included age (which needs further discussion), CA199, CA125, AFP, and CA242 were identified and might be considered as important inspection items for gastric cancer screening." (PMID 36526664, 2022). "On the other, AFP producing gastric cancer may not hepatoid adenocarcinoma." (PMID 30212993, 2018). "Several reports describe that AFP-producing gastric cancer (AFP-GC) has an aggressive clinical course and poorer prognosis than AFP-negative GC." (PMID 25962419, 2015). "Regarding the relationship between AFP production and STAT3 expression, there is no available report describing the underlying mechanisms to date.It has been reported that the AFP expression in gastric cancer is due to the lack of the transcription factor ATBF1." (PMID 23382965, 2013). "Our analysis revealed that 42% of gastric cancer cases that developed metachronous liver metastasis exhibited the GAPEP phenotype, irrespective of serum AFP elevation." (PMID 38355790, 2024). "It was also revealed that the prognosis of HER2 overexpressed AFP-GC was not worse than HER2 non-overexpressed AFP-GC, contrasted to the worse prognosis of the only HER2 overexpressed gastric cancer that had been reported." (PMID 37354221, 2023). "Through a systematic investigation of HAS and comparisons with non-HAS, we found that serum AFP level, M stage, and degree of tumor enhancement on CT are independent factors for differentiating HAS from other gastric cancers." (PMID 34956891, 2021). "In addition, the outcome of surgery for the treatment of liver metastases of alpha-fetoprotein-producing gastric cancer (AFP-GC) has not yet been reported." (PMID 32093729, 2020). "Although the incidence of AFP-producing gastric cancer (GC) is not high (approximately 1.2–15%), its aggressive features and poor prognosis have recently acquired a lot of attention for further studies such asliver metastasis, vascular invasion, and lymph node metastasis." (PMID 29254216, 2017). "Although serum AFP level is increased in the AFP-producing gastric cancer (GC) patient, AFP-producing GC may become recurrent without re-elevation of serum AFP level." (PMID 29254216, 2017). "Classic blood tumor biomarkers such as CEA, AFP, CA72-4 and CA19-9 are not sensitive enough for gastric cancer diagnosis." (PMID 27589838, 2016). "Third, the prognostic value of normal, CEA, CA19-9, AFP, and CA125 levels for gastric cancer patients after radical gastrectomy during follow-up were not investigated." (PMID 27533455, 2016). "The temporary response to TS‐1 and cisplatin suggests that adult gastric cancer regimens may represent the optimal first‐line approach for pediatric AFPGC, rather than protocols designed for other AFP‐producing tumors." (PMID 40922714, 2025). "Furthermore, to focus on the relationship between liver metastasis and GAPEP phenotype, we immunohistochemically evaluated the expression of AFP, GPC3, and SALL4 in gastric cancer with metachronous liver metastasis regardless of preoperative serum AFP levels." (PMID 38355790, 2024). "Interestingly, neither the downregulation nor overexpression of AFP affected the expression of HSP90 in liver and gastric cancer cells, as confirmed by immunoblotting." (PMID 39135041, 2024). "Although there are several commonly used serum biomarkers such as alpha-fetoprotein (AFP), carcinoembryonic antigen (CEA), cancer antigen 125 (CA125), and cancer antigen 19–9 (CA19-9) for gastric cancer diagnosis, none of them are sensitive or gastric-cancer-specific." (PMID 33717664, 2021). "In gastric cancer, VEGF expression may contribute to the higher microvessel density of the AFP-producing gastric cancers than that of the AFP-negative ones." (PMID 34680245, 2021).
gastric cancer (continued). "Moreover, we found that higher positive rates of serum CEA, AFP and CA19-9 were also correlated with older age in non-elderly gastric cancer patients." (PMID 27418046, 2016). "Serum AFP level is useful in the diagnosis and surveillance of gastric YST-like carcinoma, but was only measured after surgery in the present case, because we did not measure routinely serum AFP for gastric cancer before surgery, and did not elevate at any point." (PMID 33956241, 2021). "Serum tumor biomarkers, including carcinoembryonic antigen (CEA), α-fetoprotein (AFP), and carbohydrate antigen 19-9 (CA19-9), are often used for gastrointestinal tumor detection, but their sensitivities and specificities are not sufficient for the early diagnosis of gastric cancer." (PMID 34283058, 2021).
hepatitis B (169 papers, 1994 to 2026). "Serum AFP has a sensitivity of 68–87% and specificity of 74–90% for the diagnosis of hepatitis B associated liver cancer." (PMID 36096917, 2022). "Our study found that the AFP level was significantly associated with gender and hepatitis B virus infection status (p < 0.05)." (PMID 36556261, 2022). "Again, our observation further confirmed that serum AFP levels were associated with hepatitis B viral biomarkers positivity." (PMID 35461226, 2022). "CTNNB1 mutations are more frequent in alcohol-related HCC and associated with old age and negatively associated with hepatitis B and elevated alpha-fetoprotein, thereby mirroring the etiologic profile of the northern European HCC population." (PMID 33827453, 2021). "It was found that alpha-fetoprotein (AFP) expression increased in HBV-associated cancer cells due to hepatitis B virus infection, whereas miR-1236 expression decreased, and this could be a therapeutic approach by regulating AFP expression." (PMID 41009512, 2025). "Hepatitis B-associated HCC is reported to have higher values of AFP compared to other aetiologies." (PMID 36013482, 2022). "Second, retrospective study analysis associated with selection bias in data collection and postoperative follow-up, and finally, in this study, the main cause of HCC was hepatitis B virus infection, which is different from the common cause in Western countries, which may affect AFP secretion." (PMID 37124520, 2023). "A 55-year-old male with a history of hepatitis B presented an alpha-fetoprotein (AFP) level of 1713 ng/mL." (PMID 41204490, 2025). "A large-scale, Chinese multicenter study demonstrated a higher accuracy for HCC detection with DCP compared to AFP in hepatitis B patients." (PMID 40504251, 2025). "Previous studies have shown that MTM-HCC usually occurs in patients with hepatitis B infection and elevated serum AFP level." (PMID 40987943, 2025). "In the examination of the clinical parameters’ relevance, we discovered that chaperonin expression was associated with tumor grade, microvascular invasion (MVI0), alpha‐fetoprotein (AFP), response to sorafenib, and Hepatitis B virus (HBV) infection." (PMID 41312091, 2025). "In patients with hepatitis B, it is recommended to perform ultrasonography and measure alpha-fetoprotein levels every six months." (PMID 41379183, 2025). "Hepatitis B or C virus infection was detected in 95.6% (n = 87) of the patients with 80.34% (n = 74) classified as Child-Pugh class A. The baseline AFP levels were 419.75 ng/ml (IQR: 29.14–18061.50)." (PMID 39035736, 2024). "We screened 73 ANHC patients and found that age, ALT, AST, GGT, AFP, STIP1, and hepatitis B virus infection were significantly associated with ANHC." (PMID 38780206, 2024). "Among those demographic characteristics, blood type, sex, alpha‐fetoprotein (AFP) levels, hepatitis B and hepatitis C virus infection, total bilirubin (Tbil) are not different among the centers." (PMID 38498682, 2024). "Analyzing data from 81,520 patients in Korea, it was found that increased AFP testing significantly improved survival, particularly in patients with hepatitis B undergoing antiviral treatment." (PMID 38201578, 2023). "The forest plot indicated that patients with low-risk scores tended to be correlated with significantly longer OS in most subgroups, except for patients with female, BCLC stage B, higher AFP level, and non-B hepatitis." (PMID 37328805, 2023). "The univariate Cox regression analysis of the risk score and clinical characteristics (including gender, age, TNM stage, tumor size, hepatitis B, Lymph node invasion, vascular invasion, perineural invasion, albumin, AFP, CEA, and CA199) was performed." (PMID 35720008, 2022). "A total of 73.2% of patients had hepatitis B. At study entry, 15 (36.6%) patients had increased AFP levels, and 22 (53.7%) patients suffered from MVI." (PMID 34543520, 2022).